RNU6-1020P (RNA, U6 small nuclear 1020, pseudogene)
Gene: Small nuclear RNA gene on chromosome 9 (125,303,920 to 125,304,026, reverse strand). Ensembl gene ENSG00000200554.
Homologues: Orthologues: chimpanzee U6 (100% identical), macaque U6 (85% identical), rat LOC120101955 (80% identical), mouse Gm23354 (79% identical). Paralogues in human: RNU6-12P (91% identical), RNU6-13P (91% identical), RNU6-24P (91% identical), RNU6-32P (91% identical), RNU6-33P (91% identical), RNU6-1 (90% identical), RNU6-11P (90% identical), RNU6-17P (90% identical), RNU6-18P (90% identical), RNU6-2 (90% identical), RNU6-37P (90% identical), RNU6-3P (90% identical), and 1287 more.